GBA1 (glucosylceramidase beta 1)
Diseases named in the same sentence as GBA1 in open-access papers (continued):
Sharing a sentence is not in itself a finding about the gene and the disease.
lysosomal storage disorder (continued). "Biallelic pathologic variants in GBA1 are associated with Gaucher disease (GD), a recessive lysosomal storage disorder characterized by a deficiency in the hydrolyzing lysosomal enzyme glucocerebrosidase (GCase)." (PMID 34202076, 2021). "Gaucher disease, one of the most common lysosomal storage disorders, is caused by the mutation of the GBA1 gene, resulting in the defective activity of a lysosomal enzyme called glucocerebrosidase (GCase, β-glucosidase; EC: 3.2.1.45)." (PMID 34163514, 2021). "GD is the most common of the lysosomal storage diseases, and it is caused by a hereditary deficiency of the enzyme GCase, which is encoded by a gene named GBA1." (PMID 34744624, 2021). "Gaucher disease (GD) is a lysosomal storage disorder caused by a mutation in the glucocerebrosidase 1 (GBA1) gene, resulting in the deficiency of the enzyme glucocerebrosidase (GCase)." (PMID 33297340, 2020). "Recent genetic studies have revealed that mutations in the glucocerebrosidase (GBA1) gene cause Gaucher disease (GD), the most common lysosomal storage disorder, and increase susceptibility to PD and α-syn pathology." (PMID 33330511, 2020). "Gaucher disease, the most common lysosomal storage disease in humans, is caused by a deficiency in the lysosomal enzyme glucocerebrosidase (hGCB; GBA1; glucosylceramidase; acid β-glucosidase; EC 3.2.1.45)." (PMID 27228111, 2016). "Gaucher disease type 1, an inherited lysosomal storage disorder, is caused by mutations in GBA1 leading to defective glucocerebrosidase (GCase) function and consequent excess accumulation of glucosylceramide/glucosylsphingosine in visceral organs." (PMID 24124461, 2013). "Gaucher disease (GD) is the most common inherited lysosomal storage disorder in humans, caused by mutations in the gene encoding the lysosomal enzyme glucocerebrosidase (GBA1)." (PMID 24070122, 2013). "GD is a rare hereditary lysosomal storage disorder caused by defects in the GBA1 gene." (PMID 36776904, 2023). "Accumulating evidence suggests that mutations in genes related to lysosomal function or lysosomal storage disorders may affect the risk of PD development, such as GBA1 gene mutations." (PMID 33036336, 2020). "Collectively, these findings demonstrate the potential of GCase-BS for treating GBA1-associated lysosomal dysfunction, provide insight into candidate biomarkers, and may ultimately open a promising treatment paradigm for lysosomal storage diseases extending beyond the central nervous system." (PMID 37045813, 2023). "METHODS: Using Drosophila melanogaster, we performed a genetic interaction screen of lysosomal storage disorder (LSD) genes to identify dominant modifiers of Gba1b (fly homolog of GBA1)." (PMID 41618357, 2026). "The data generated by WES were evaluated for monogenic PD, lysosomal disorders, and genetic modifiers of GBA1 in PD." (PMID 40542290, 2025). "Several genes, such as SNCA, LRRK2, GBA1, ATP13A2, and VPS35, among the pathogenic ones related to familial PD, are associated with lysosomal storage disorders." (PMID 35720097, 2022). "Gaucher disease is a rare pan-ethnic, lysosomal storage disorder resulting due to beta-Glucosidase (GBA1) gene defect." (PMID 30764785, 2019). "Gaucher disease (GD), the most common lysosomal storage disease (LSD), is caused by mutations in the GBA1 gene, which encodes for glucosylceramidase (GlcCerase), the lysosomal hydrolase responsible for glucosylceramide (GlcCer) degradation." (PMID 25775479, 2015). "Comparative models targeting Gba1 deletion prenatally versus postnatally, combined with transcriptomic profiling, will be essential for defining the evolving role of microglia across disease stages and for developing more effective therapeutic platforms for nGD and related lysosomal disorders." (PMID 41465340, 2025).
dementia (125 papers, 2013 to 2026). Loss of intellectual abilities interfering with an individual's social and occupational functions. "Dementia risk was associated with GBA1 status (HR = 3.04, 95% CI = 1.05-8.79, p = 0.041), baseline MoCA < 26 (HR = 3.05, 95% CI = 1.29-7.21, p = 0.011), and baseline age > 69 years (HR = 4.42, 95% CI = 1.79-10.89, p = 0.001)." (PMID 41542740, 2026). "Individuals carrying GBA1 mutations exhibit an increased risk of developing dementia within the context of PD and Lewy Bodies Disease." (PMID 40687116, 2025). "In this study, EVs were derived from post-mortem cerebrospinal fluid (CSF) of GBA1 mutation carriers with PD, as well as with dementia and Lewy bodies." (PMID 41009720, 2025). "Approximately 5–20% of PD patients carry a heterozygous GBA1 mutation (GBA-PD), differentiated by a 30–40% reduction in GCase activity, earlier disease onset including an increased risk for developing dementia with an up to five years earlier onset." (PMID 40333681, 2025). "Defective glycosphingolipid transport and degradation-especially via the lipid-degrading enzyme glucocerebrosidase 1 (GCase, gene GBA1)-aggravate PD and increase dementia risk." (PMID 41361659, 2025). "GBA1 PD carries more risk of dementia, whereas LRRK2 PD appears to have a more restricted pattern of neurodegeneration and reduced risk of dementia." (PMID 40926580, 2025). "GBA1 and lysosomal genes: Heterozygous mutations in GBA1, which encodes glucocerebrosidase (GCase), impair lysosomal function and increase the risk of Parkinson's disease (PD) and dementia with Lewy bodies." (PMID 41585268, 2025). "Compared to non-carriers, PD carriers had a more severe UPDRS motor score and the occurrence of dementia was significantly predicted by the GBA1 mutation status." (PMID 39766872, 2024). "The association of GBA1 variants with PD and dementia (GBA1-associated Parkinson’s disease) has been extensively studied over the past few years." (PMID 37189391, 2023). "ApoE and GBA1 are the most significant combined genetic risk factors for LBD and related dementias, and the in vivo experiments reported here tested functional and brain regional responses to GBA1 inhibition and loss of ApoE in mice models." (PMID 37947642, 2023). "The increased risk of mortality associated with carrying any GBA1 variant persisted after controlling for dementia status (HR 2.0 (95% CI 1.0 to 4.1, p=0.046)), suggesting that the relationship was independent of the development of dementia." (PMID 32303560, 2020). "We have demonstrated that GBA1 variants confer an increased risk of dementia, faster motor progression and mortality in PD, in keeping with previous reports." (PMID 32303560, 2020). "Heterozygous GBA1 mutations are encountered in 7–12% of PD patients (GBA1-PD) and shown to increase risk for motor symptom severity and dementia progression." (PMID 33381501, 2020). "In patients with PD and GBA1 mutations, age at PD diagnosis is younger and dementia is usually more severe." (PMID 29595653, 2018). "The association between GBA1 mutations and synucleinopathies other than PD and dementia with LBD, such as multiple system atrophy, still remains controversial." (PMID 30002620, 2018). "Additionally, GBA1 mutations have been linked to dementia with LBs, further underscoring the connection between GBA1 mutations and alpha-synucleinopathies." (PMID 39000225, 2024). "GBA1 mutations are known to confer an increased risk for dementia in PD and DLB." (PMID 39606324, 2024). "Interestingly, the phenotype of individuals with PD carrying GBA1 variants is characterized by faster progression and a higher frequency of dementia compared to noncarriers." (PMID 39668204, 2024). "Deficient α-synuclein clearance mechanisms in GBA1 mutants leading to intensified α-synuclein accumulation in cortical areas is considered to exacerbate cognitive impairment and, in the long run, induce dementia in GBA1-PD patients." (PMID 36768367, 2023).
dementia (continued). "The authors concluded that the imaging findings could provide a confirmation of the more severe disease course in GBA1-PD patients and their higher susceptibility for executive function decline, dementia, and visual hallucinations." (PMID 37626568, 2023). "Our observation that N370S GBA1 cholinergic cells have increased levels of these two proteins may help provide an explanation for the earlier onset and more rapid progression of dementia associated with this mutation." (PMID 35179198, 2022). "Deficient clearance mechanisms of a-synuclein in GBA1 mutants leading to accelerated a-synuclein pathology in cortical areas is thought to underlie the increased rates of cognitive impairment and ultimately, dementia in GBA1-PD patients." (PMID 35932311, 2022). "GBA1 mutation(s) also increases one’s risk of developing PD, from 5× for mono-allelic carriers to up to 20× for bi-allelic carriers, as well as of related neurodegenerative disorders such as Lewy Body Dementia or Parkinson’s Disease Dementia." (PMID 34151863, 2021). "The significant correlation between the severity of the specific GBA1 mutation and that of clinical phenotypes (e.g., odds ratios for PD, age at onset, risk for dementia) has been reported, suggesting major impact of GCase activity in the pathogenetic processes." (PMID 34194386, 2021). "Furthermore, it has also been postulated a relationship between the type of GBA1 mutation variant and the risk of PD and dementia." (PMID 34062940, 2021). "Moreover, the association of GBA1 mutations and dementia with Lewy bodies (LBD) is even stronger than for PD." (PMID 30002620, 2018). "Generally, mutations in GBA1 are associated with a more severe clinical progression, including earlier age of onset, earlier and more severe cognitive impairment with a shorter time to dementia and higher frequency of neuropsychiatric symptoms compared to idiopathic PD2–7." (PMID 38951174, 2024). "There have been reported genetic links between GBA1 and other α-synuclein diseases such as dementia with Lewy bodies or multiple system atrophy." (PMID 40333681, 2025). "One GBA1-PD converter exhibited clinical characteristics of dementia with lewy bodies (DLB) already at baseline, consequently being excluded from the longitudinal analyses." (PMID 38649346, 2024). "REM sleep behaviour disorder, a precursor of dementia in PD25–27, was more frequent in GBA1 mutation carriers, as previously reported by others." (PMID 39420034, 2024). "The loci highlighted by LAVA further strengthen this theory, as GBA1 variants are commonly associated with worse cognitive outcomes in PD patients, and it has been suggested that MAPT is associated with dementia in PD25." (PMID 39639040, 2024). "The more extensive neocortical Lewy body-type lesions in patients with GBA1-PD, and the higher rate of GBA1 mutation in patients with dementia with Lewy bodies (DLB), also reflect, to some extent, the close relationship between PD and dementia." (PMID 39267121, 2024). "ABX is currently studied (also IIRs) as a PC therapy for patients with GBA1-related and idiopathic PD, and in GBA1-related dementia; it will soon be studied for the prevention of GBA1-related PD in individuals with advanced prodromal features." (PMID 37047707, 2023). "In 2012, a case series of three PD-GBA1 and six non-GBA1 carriers showed a higher prevalence of dementia in the PD-GBA1 group after 24 to 48 months of STN-DBS." (PMID 37122287, 2023). "These cells and their isogenic controls were then differentiated to cortical neuronal fate, given the unique prevalence of dementia in GBA1-PD and the prevalence of αSyn throughout both cortical and sub-cortical brain regions in PD." (PMID 32499675, 2020). "All patients in the GBA1 carrier group had developed dementia or died prior to the 15-year time point." (PMID 32303560, 2020).
dementia (continued). "Regarding cognition, GBA1-PD patients demonstrated a significantly lower mean score on the MoCA scale and a higher prevalence of dementia compared to mutation-negative controls." (PMID 39766872, 2024). "Its ability to reduce tau, phospho-tau and α-syn in cholinergic cells, as well as α-syn in dopaminergic cells, could represent an important protective mechanism against dementia in PD, and GBA1-PD in particular." (PMID 35179198, 2022). "Pathogenic GBA1 variants were associated with earlier mortality in comparison with non-carriers, independent of the development of dementia." (PMID 32303560, 2020). "Pathogenic and ‘non-pathogenic’ GBA1 variants were associated with the accelerated development of dementia and a more aggressive motor course." (PMID 32303560, 2020). "Carriers of any GBA1 variant had an increased risk of progression to dementia compared with non-carriers." (PMID 32303560, 2020). "Whether APOE E4 carrier status poses a similar risk of dementia in LRRK2 and/or GBA1 PD is unknown." (PMID 40926580, 2025). "Cox regression analysis controlling for age at diagnosis, sex and baseline MMSE score revealed that development of dementia was significantly more likely in carriers of any GBA1 variant, compared with non-carriers, with an HR of 2.1 (95% CI 1.2 to 3.9, p=0.013)." (PMID 32303560, 2020). "Carriers of any GBA1 variant had a projected mean time to dementia that was approximately 5 years earlier than in non-carriers, while the estimated mean time to development of postural instability was approximately 2 years earlier than that seen in non-carriers." (PMID 32303560, 2020). "While dementia, probable RBD, and psychosis were more prevalent in GBA1-PD, these manifestations appear to be less frequent for LRRK2-GBA1-PD." (PMID 39766872, 2024). "Several intensively studied dementia-affiliated genes such as APOE (apolipoprotein E), GBA1 (glucosylceramidase beta 1), LRRK2 (leucine rich repeat kinase 2), and PINK1 (PTEN induced kinase 1) encode proteins that function in the human metabolism." (PMID 36771351, 2023). "GBA1-PD showed a significant lower mean MoCA score, and higher percentage of dementia compared to negative controls (p 0.04)." (PMID 39034353, 2025). "In addition, the odds of REM sleep behaviour disorder, which is often a precursor of cognitive decline and dementia in PD25–27, were significantly increased in GBA1 carriers (OR = 1.79, 95% CI = 1.02–3.11, P = 0.041)." (PMID 39420034, 2024). "GBA1-PD patients with EOPD performed worse in cognition assessment tests like MMSE in comparison to age-matched non-carriers and fulfilled diagnostic criteria for dementia more frequently." (PMID 39766872, 2024). "Key subtle traits of GBA1-PD have since emerged notably, an earlier age of onset by ~ 1.7–6.0 years, higher Unified Parkinson’s Disease Rating Scale Part III (UPDRS-III) scores, greater frequency of dementia, visual hallucinations and severity of NMSs, particularly depression." (PMID 35932311, 2022). "GBA1 mutations are also a risk factor for dementia with Lewy bodies (DLB), and PD patients with GBA1 mutation have about a 3-fold higher risk of progressing to dementia than those without mutation." (PMID 34194386, 2021).
Parkinsonism (94 papers, 2012 to 2026). Characteristic neurologic anomaly resulting from degeneration of dopamine-generating cells in the substantia nigra, a region of the midbrain, characterized clinically by shaking, rigidity, slowness of movement and difficulty with walking and gait. "This study describes the full landscape of GBA1-related parkinsonism in Luxembourg, showing a high prevalence of GBA1 variants as the major genetic risk for PD." (PMID 37996455, 2023). "Since the comorbidity of Parkinsonism among GD patients and GBA1 mutation carriers was first recognized in the clinics, the association of the GBA1 mutation with PD development has been independently reported by many association studies." (PMID 33672048, 2021). "After initial incidental descriptions of GD patients with parkinsonism, a higher incidence of PD among GBA1 mutation carriers was found; GBA1 mutations confer a 20–30-fold increased risk to develop PD, and overall, 5–10% of PD patients have been found to carry GBA1 variants." (PMID 35842725, 2022). "In addition to pathogenic mutations in well-established PD-related genes (LRRK2, PRKN, PINK1, SNCA, PLA2G6 and GBA1), we identified pathogenic mutations in genes that have been reported to present as levodopa-responsive parkinsonism but typically present with alternative or atypical phenotypes." (PMID 39420034, 2024). "Other genes excluded from the PARK category, such as GBA1, GTP cyclohydrolase 1 (GCH1), and MAPT, were also significantly linked to PD or parkinsonism through meta-analyses of GWAS." (PMID 35720097, 2022). "Although the studies have partially relationship among GBA1, α-synuclein, and PD, the animal models fail to represent GBA1-associated Parkinsonism, lacking an earlier age of PD onset and dopaminergic neurodegeneration." (PMID 29703245, 2018). "Similarly, GBA1 mutation carriers are at elevated risk of DLB, which shares overlapping pathology with PD (i.e., Lewy body disease) and is characterized by early cognitive impairment, visual hallucinations, fluctuations and parkinsonism." (PMID 41465169, 2025). "However, these animal models do not fully represent the clinical observations seen in the GBA1-associated Parkinsonism such as earlier PD onset and DA neuronal loss." (PMID 29703245, 2018). "Over 300 mutations in GBA1 have been identified to date; patients with GCase-associated parkinsonism exhibit varied parkinsonian phenotypes but tend to present with slightly earlier age of onset and higher prevalence of cognitive changes compared to PD patients without GBA1 mutations." (PMID 34106956, 2021).